IFNG (interferon gamma)
Diseases named in the same sentence as IFNG in open-access papers (continued):
Sharing a sentence is not in itself a finding about the gene and the disease.
tumor (continued). "Using vaccinia virus and EL4 tumor models expressing the same antigen, we found that Tum-CD8+ cells displayed a distinct phenotype, including sustained expression of inhibitory receptors (PD-1, TIM-3), altered integrin expression, and reduced production of IFNγ and TNF." (PMID 42023146, 2026). "We found that Tbet+ICOS+ Th1-like CD4+ T cells expressed the highest level of PD-1 among tumor-infiltrating CD4+ Tconv, indicative of high tumor reactivity, and that in vivo treatment with 9D9 increased the proportion of PD-1+ CD4+ T cells producing IFNγ upon re-stimulation ex vivo." (PMID 40460830, 2025). "Furthermore, to confirm tumor antigen-specific T cell responses rather than nonspecific T cells activation, we stimulated tumor-derived single cells with either DMSO or gp100, a B16 tumor-associated antigen, then assessed IFNγ-producing CD8+ T cells." (PMID 41339438, 2025). "We exposed the TIL products for 6–7 h to autologous tumor digest, and we measured the expression of the activation marker CD137 (4-1BB) indicative of TCR triggering, the degranulation marker CD107a, and TNF and IFNγ required for effective antitumoral responses." (PMID 40897471, 2025). "Interestingly, high expression of GZMA, GZMB, IFNG, and PRF1 in exhausted T-cells may be attributed to feedback responses due to complex interactions with other stromal cells in the tumor microenvironment (TME)." (PMID 40236693, 2025). "Additionally, Huaier may promote the secretion of immune-stimulating cytokines such as interferon-gamma (IFN-γ), further boosting anti-tumor immunity and inhibiting metastatic processes." (PMID 40573279, 2025). "IFNα and IFNγ can bind to their respective receptors and activate several pathways, including the JAK-STAT pathway, to coordinate different cell functions, such as immune regulation, leukocyte transportation, cell proliferation, apoptosis, and antimicrobial, antitumor, and pro-tumor effects." (PMID 39904787, 2025). "Moreover, the neutralization of IFNγ, but not TNFα, significantly attenuated birinapant-induced immune-dependent anti-tumor activity." (PMID 40057483, 2025). "The increase in IFNγ signaling and antigen presentation after tebentafusp treatment may also enhance the response to a second TCR-CD3 T cell engager targeting a different tumor antigen, through increased T cell responsiveness and increased target presentation." (PMID 40239619, 2025). "Furthermore, combination therapy increased IFNγ-producing CD8+ T cell populations and enhanced CTL-mediated cytotoxicity, suggesting that 7k augments antitumor immunity through both T cell activation and direct tumor targeting." (PMID 41155994, 2025). "This, in turn, activates CD8+ T cells, triggering interferon-gamma (IFN-γ)-mediated downregulation of SLC7A11 and establishing a self-amplifying cascade of “ferroptosis-autophagy-immunity” loop that induces oxidative stress and leads to enhanced anti-tumor effects." (PMID 40963899, 2025). "Our results suggest that p300 engagement and subsequent myeloid mimicry occur via the binding of IFNγ to the IFNGR1 that is overexpressed in RMC tumor cells after ICT, representing a non-canonical downstream pathway of interferon gamma signaling that promotes lineage plasticity." (PMID 41290625, 2025). "However, neither the IL‐2 and IFNγ levels nor the surface expression of CD69 of T cells activated by I3A‐treated tumor cells was changed by autophagy inhibitors." (PMID 40583248, 2025). "Secreted BiTEs not only recruit bystander T cells to eliminate antigen-negative tumor clones (overcoming heterogeneity) but also ‘re-educate’ the TME as evidenced by the conversion of immunosuppressive Tregs into IFNγ-producing cytotoxic effectors in patient CSF samples." (PMID 41154636, 2025).
tumor (continued). "To see whether similar results are found in M1 macrophages polarized by stimuli other than IFNγ + LPS and M2 macrophages by IL-4 or TGF-β1, we stimulated the macrophages with a tumor conditioned media of 2D- (2D TCM) or 3D-cultured tumor cells (3D TCM), IFNγ alone, TNFα, IL-4 or TGF-β1." (PMID 40050422, 2025). "Notably, B2m expression exhibited significant attenuation in response to IFNγ for DKO cells, suggesting that MBNL proteins contribute to the modulation of the tumor-immune interaction in part via alterations in expression levels of components of MHC Class I antigen presentation." (PMID 40305509, 2025). "Besides, non-mineralized IFNγ and Zole were then adopted for intratumoral injection to supplementarily investigate the anti-tumor efficacy of two free drugs and their physical mixture." (PMID 39776793, 2025). "This tendency was not seen when autologous tumor cells were pre-stimulated with IFNg." (PMID 40107242, 2025). "M1, induced by interferon-gamma (IFN-γ) and lipopolysaccharide (LPS), express high levels of inducible nitric oxide synthase (iNOS), interleukin (IL)-12, and tumor necrosis factor-alpha (TNF-α), promoting anti-tumor immunity through direct cytotoxicity and T cell activation." (PMID 40806379, 2025). "However, Mettl5 KO in murine OC cells did not reduce IFNγ production by tumor‐reactive CD8+ T cells after tumor stimulation, suggesting that loss of Mettl5 minimally affects immune synapse formation between CD8+ T cells and tumors." (PMID 41042068, 2025). "Not all CAR T cells that generates IFNγ is lysing the tumor cells." (PMID 40416968, 2025). "IFNγ is produced significantly by macrophages, activated CD8 T cells, natural killer T cells, and Th1 CD4 T cells, whereas Tregs may inhibit anti-tumor immunity." (PMID 40852728, 2025). "While the magnitude of increase in IFNγ and CXCL10 in response to αCD3/αCD28 between cross-well and sequential treatment varied, the directionality of response was in high agreement with 5/6 tumor samples showing >1.5 fold change for IFNγ and all tumor samples showing >1.5 fold change for CXCL10." (PMID 40791544, 2025). "In addition, IL‐12‐activated NCR+ ILC3s have been shown to promote tumour rejection, not through cytotoxicity or IFNγ production, but by inducing expression of adhesion molecules like VCAM‐1 and ICAM‐1 on tumour vasculature, enhancing immune cell infiltration." (PMID 40899118, 2025). "Moreover, PD-L1 expression represents a dynamic phenotype that fluctuates in response to inflammatory cytokines, particularly interferon-gamma, rather than a fixed tumor characteristic." (PMID 40649844, 2025). "Interestingly, immune checkpoints on CD8+ T cells were downregulated with selinexor at the tumour site, and although not significant, granzyme B and IFNγ expression were increased, highlighting an active immune response within the TME with selinexor." (PMID 40291981, 2025). "Consequently, the lack of IFNγ in the TME is supposed to be a significant mechanism of tumor immune escape and strikingly contributes to cancer treatment failure." (PMID 41345386, 2025). "For example, if there are active immune activation signals between some tumor subpopulations and T cells (such CD80/CD28 or IFNG/IFNGR), it could mean that the patient is more likely to respond to immunity therapy and could benefit from immune checkpoint inhibitors." (PMID 40842994, 2025). "A study elucidated that interferon-gamma (IFN-γ) released from CD8+ T cells can downregulate the expression levels of SLC3A2 and SLC7A11 on the tumor cell surface, thereby suppressing cystine uptake by tumor cells and ultimately promoting tumor cell lipid peroxidation and ferroptosis." (PMID 40260246, 2025). "We also measured the IFNγ production of the tumor‐infiltrating lymphocytes (TILs) isolated from the EG7 or B16 tumors with I3A or vehicle treatment via IFNγ ELISpot assay, and the result showed that I3A treatment boosted IFNγ production level in the TILs of both tumor models." (PMID 40583248, 2025).
tumor (continued). "Besides the effect of L-Leu removal in the restriction of KLN205 tumor growth, a substantial GVT response was observed, which might be explained by the activation and preservation of IFNγ response by allogenic CD8+ T cells." (PMID 40399490, 2025). "On days 7, 12, 17, and 22 following A549 cells inoculation, human anti-IFNγ neutralizing mAb or rhIFNγ was injected into mice intraperitoneally, and after 12 h, BSA-, PA-, or OA-treated Vγ9Vδ2-T cells were administered intravenously to tumor-bearing mice, respectively." (PMID 40603316, 2025). "Neither human anti-IFNγ antibody nor rhIFNγ has a direct influence in the tumor growth." (PMID 40603316, 2025). "We assume the mild anti-tumor effect of non-mineralized IFNγ or Zole may be attributed to their immune regulation effect." (PMID 39776793, 2025). "The single-cell suspensions of the tumor mass or bone marrow were stimulated for 4 h with the NK1.1 antibody or a cytokine cocktail containing IL-12 and IL-15, followed by analysis of NK cell degranulation via CD107a surface expression and NK cell activation by IFNγ staining." (PMID 39885132, 2025). "(i) SFV/IFNγ-induced macrophage reprogramming may synergise with other TME-targeted therapies, such as TLR agonists or CTL-activating agents (checkpoint inhibitors), to achieve durable anti-tumour responses." (PMID 40547518, 2025). "However, there is no consensus on the number of genes to include in this IFNγ signature and, unlike the sCD27 marker, it requires a tumor biopsy." (PMID 40148586, 2025). "Thus, while monocytes need CD8+ T cells for their recruitment regardless of the tumour type, inhibition of IFNγ sensing in tumours leads to an increase in the ability of CD8+ T cells to recruit monocytes." (PMID 39746898, 2025). "Importantly, effector cells isolated from these long-term survivors and co-cultured with CT2A-Par cells released IFNγ in a dose dependent manner whereas effector cells isolated from naïve (non-tumor bearing) mice did not." (PMID 39399681, 2024). "Together, this supports the hypothesis that increased IFNγ production, from non-cell autonomous sources, is driving elevated IDO1 expression in tumour epithelial cells in Dock2 deficient mice." (PMID 39242821, 2024). "Furthermore, tumor infiltration by IFNγ-expressing CD8 + T cells was increased in the Cpt1a ablated/7.16.4 mAb-treated tumors compared with control groups, consistent with the recruitment and activation of cytotoxic, anti-tumor leukocytes." (PMID 39097623, 2024). "This could reflect a limitation in the experimental approach, where in vivo neutralization of IFNγ is sufficient to have a measurable effect on MHC-I expression but not tumor cell deletion." (PMID 38565540, 2024). "Interferon gamma (IFN-γ) released by CD8+ T cells downregulates the expression of two subunits, SLC3A2 and SLC7A11, of the glutamate-cysteine antiporter system, impairing tumor cell uptake of cysteine, thereby promoting lipid peroxidation and ferroptosis in tumor cells." (PMID 38753091, 2024). "However, the specific regulatory effects of IFNγ and STAT1 signaling pathways in the anti-tumor immune response are still unknown." (PMID 38167862, 2024). "Inflammatory cytokines TNF-α, IL-12 and IFNγ were increased especially in cell cultures with spleen cells from WT mice treated in vitro with BCG, but not with spleen cells from MyD88-/-, reinforcing the importance of MyD88 to induce cell death mechanisms and tumor control." (PMID 38835781, 2024). "However, prolonged exposure to interferon-gamma transforms teammates into adversaries, producing pro-tumorigenic effects through immunosuppression (PDL1, IDO1, Fas, and FASL), angiogenesis (CXCL9, CXCL10, CXCL11, IDO1, and iNOS), and tumor cell proliferation." (PMID 39835116, 2024).
tumor (continued). "IFNγ released by CD8(+)T cells inhibits the expression of SLC7A11 synergistically, leading to the activation of ferroptosis, thereby enhancing anti-PD-L1 anti-tumor immunotherapy, enhancing lipid oxidation and ferroptosis in tumors, and improving tumor control." (PMID 39192972, 2024). "This enhancement is further characterized by increased production of interferon-gamma (IFN-γ) and interleukin-2 (IL-2) within the TME, concurrent with downregulation of tumor necrosis factor-alpha (TNF-α) and interleukin-10 (IL-10), thereby fortifying the host’s anti-tumor defenses." (PMID 38930435, 2024). "However, under these conditions, B16 tumor cells had only low levels of MHC-I and MHC-II, but expression could be induced with recombinant IFNγ stimulation." (PMID 38565540, 2024). "Interestingly, IFNγ produced by activated CD8+ T cells inhibits the expression of SLC3A2 and Solute Carrier Family 7 Member 11 (SLC7A11), components of the cystine/glutamate antiporter system xc-, promoting lipid peroxidation and ferroptosis in tumor cells." (PMID 39273090, 2024). "As expected, the proportion of IFNγ-producing cells among degranulated CD107a+ pNK cells exceeded the IFNγ production level in the CD107a-negative pNK cell fraction for all three types of tumor spheroids analyzed." (PMID 39457710, 2024). "Conversely, IRG1 knockout (KO) in EG7 tumor cells via the CRISPR/Cas9 technique not only abolished itaconate production induced by thimerosal treatment but also markedly attenuated the IFNγ production and IL-2 promoter-driven LacZ activity in T cells co-cultured with EG7 cells." (PMID 39349845, 2024). "Whether H. pylori–induced or not, lymphocytes and other tumor-infiltrating immune cells can nonetheless secrete proinflammatory cytokines such as TNFα and IFNγ." (PMID 39461475, 2024). "This secretion of interferon-gamma (IFN-γ) can prompt cancer cells to increase the expression levels of Major Histocompatibility Complex-I (MHC-I) and CD86.Ultimately, this upregulated expression of MHC-I and CD86 can enhance T-cell-mediated anti-tumor immune responses." (PMID 39655080, 2024). "However, in a model of T cell exhaustion, 89Zr-anti-IFNγ tumor uptake was no different from mice imaged with isotype control." (PMID 39104861, 2024). "VHH-2-Hc showed almost no IFNγ release, which we hypothesized as insufficient to support tumor inflammation and downstream endogenous anti-tumor immunity." (PMID 38455046, 2024). "Indeed, our study demonstrates that systemic IFNγ/α treatment in combination with anti-PD1 resulted in a non-significant reduction in tumor growth and no change in cytotoxic CD8+ T cell activation." (PMID 38181798, 2024). "Overexpression of MCT11 resulted in accelerated functional exhaustion, as these T cells had decreased TNF and interferon γ (IFNγ) production, although no appreciable changes were observed in tumor infiltration or coinhibitory marker expression when compared with EV controls." (PMID 39516648, 2024). "Whereas, tumor-infiltrating T cells in IFNγ+/- cKO mice almost did not secret IFNγ." (PMID 38167862, 2024). "Additionally, in agreement with the results obtained with the B16-OVA model, the numbers of tumor-infiltrating CD45+, granzyme B- or IFNγ-producing CD8+ T cells and CD4+ T cells were significantly greater in the TOFA-treated Th9 group than in the untreated Th9 cell group." (PMID 39187636, 2024). "However, IL-33 neutralisation in vivo led to a more quiescent tumour characterised by the infiltration of CD4+ T cells producing interferon gamma (IFNγ) (Th1-like) and decreased Th2-like cells (CD8+ and CD4+ T cells expressing IL-4) in the tumour microenvironment." (PMID 38662248, 2024). "Notably, selective ablation of both alleles of CARD11 in Tregs endowed fatal immune pathology, while partial deletion of CARD11 in only a fraction of Tregs to provoke their production of the IFNγ and TNF was sufficient to generate anti-tumor effects and avoid detectable immune pathology." (PMID 39227959, 2024).
tumor (continued). "Additionally, we found more tumor-specific T cells with a stem-like (TCF1+ TIM3- PD1+) and a transitory (TCF1- TIM3+ CD101- PD1+) exhausted phenotype and more expressing effector molecules such as GzmB, IFNγ, and TNFα." (PMID 38646638, 2024). "Finally, an increase in IFNγ expression by both CD8+ T cells and NK cells, as well as an increase in the number of CD8+ T cells, occurred during subsequent treatment stages, resulting in durable protection against tumor rechallenge." (PMID 38109851, 2024). "Upon binding to the target antigen expressed on tumor cells, CAR-T cells undergo activation, leading to the secretion of cytotoxic molecules such as perforin and granzyme, as well as the release of pro-inflammatory cytokines such as interferon-gamma (IFN-γ) and tumor necrosis factor-alpha (TNF-α)." (PMID 39000281, 2024). "The analysis revealed the tumor-specific functional activation of the following processes: cell surface interactions at vascular wall, glycolysis, MTORC1 signaling, serine/threonine kinase activity, angiogenesis, interferon alpha/beta signaling, and interferon gamma signaling." (PMID 39315092, 2024). "In the ENTPD1/ITGAE double positive (tumor‐reactive, tr) population, local TCR clonal expansion and PD‐1 expression were used to classify the following four clusters of effector T cells (Teff): the TOP2A+ proliferating prTeff, IFNGhigh trTeff, IFNGlow trTeff, and IFNG−/CXCR6+ trTeff (trTeff‐CXCR6)." (PMID 38582099, 2024). "However, tumor cell death is decreased after co-treatment with AMG-232 and IFNγ." (PMID 39237877, 2024). "Thus, enhanced IFNγ secretion by effector CD8 cells lacking MCJ contributes to the superior anti-tumor killing activity of these cells." (PMID 38789421, 2024). "Furthermore, in NK cells, the generation capacity of IFNγ and perforin were dramatically increased on day 7 after treatment, with downregulated levels of CTLA-4 and Tim-3 compared to those in the tumor-bearing controls, suggesting the activation and improved cytotoxicity after cryo-thermal therapy." (PMID 38827732, 2024). "Moreover, our bioinformatic analyses in individuals with cancer demonstrate that CDA levels are highest in 11 different tumor types with immunosuppressive features (that is, high in P2RY6, MRC1 and MSR1 levels in macrophages and low in IFNG and PRF levels in CD8+ T cells)." (PMID 38844817, 2024). "Interestingly, the in vitro IFNγ-inducibility of PD-L1 and MHC-I correlates with tumor outgrowth." (PMID 39009951, 2024). "Importantly, in vitro antibody-mediated neutralisation of ILC2-derived IL-4 and IL-13 reduced tumour MDSC Arg1 levels, and similarly genetic deletion of IL-13 in mice with CRC decreased Arg1+ MDSCs, increased IFNγ production by Th1 cells and CD8+ T cells, and significantly reduced tumour burden." (PMID 38464388, 2024). "Importantly, blockade of IFNγ through anti-IFNγ antibody (Ab) treatment, abolished the anti-tumor therapeutic effect of SRC-3 KO Tregs, which further solidifies the centrality of the IFNγ/CXCL9 axis to SRC-3 KO Treg-mediated tumor clearance." (PMID 38698860, 2024). "Thus, there is no activation of tumor infiltrating T lymphocytes and, consequently, there is no secretion of interferon gamma, which is essential for the adaptive expression of PD-L1 by tumor cells." (PMID 38954689, 2024). "To determine whether the efficacy of FS120m is dependent on IFNγ produced specifically by Tregs and their lineage-instable progeny, we treated Ifngfl/flFoxp3EGFP-Cre-ERT2 and IfngWTFoxp3EGFP-Cre-ERT2 mice with tamoxifen before tumor implantation." (PMID 38995700, 2024). "In this study, loss of IFNγR signaling emerged as a sensitizing pathway for CAR-T killing in an aggressive murine model of B-ALL, yet blockade of IFNγ cytokine by antibody did not enhance susceptibility to CAR-T cells, and, rather, resulted in abrogation of anti-tumor effects of CAR-T cells." (PMID 38052854, 2023).